BBS7 (Bardet-Biedl syndrome 7)
Description:
The BBSome complex is thought to function as a coat complex required for sorting of specific membrane proteins to the primary cilia. The BBSome complex is required for ciliogenesis but is dispensable for centriolar satellite function. This ciliogenic function is mediated in part by the Rab8 GDP/GTP exchange factor, which localizes to the basal body and contacts the BBSome. Rab8(GTP) enters the primary cilium and promotes extension of the ciliary membrane. Firstly the BBSome associates with the ciliary membrane and binds to RAB3IP/Rabin8, the guanosyl exchange factor (GEF) for Rab8 and then the Rab8-GTP localizes to the cilium and promotes docking and fusion of carrier vesicles to the base of the ciliary membrane. The BBSome complex, together with the LTZL1, controls SMO ciliary trafficking and contributes to the sonic hedgehog (SHH) pathway regulation. Required for proper BBSome complex assembly and its ciliary localization.
Synonyms: BBS2L1; FLJ10715
Tractability: Antibody: its Gene Ontology location is reachable by antibodies, with medium confidence. PROTAC: ubiquitination databases record sites on it.
Gene: Protein-coding gene on chromosome 4 (121,824,329 to 121,870,494, reverse strand). Ensembl gene ENSG00000138686.
Subcellular location: Cell projection, cilium membrane; Cytoplasm; Cytoplasm, cytoskeleton, microtubule organizing center, centrosome, centriolar satellite; Cytoplasm, cytoskeleton, cilium basal body
Pathways (Reactome):
Organelle biogenesis and maintenance: BBSome-mediated cargo-targeting to cilium
Gene Ontology:
Molecular function: protein binding; RNA polymerase II-specific DNA-binding transcription factor binding
Biological process: positive regulation of proteasomal ubiquitin-dependent protein catabolic process; regulation of transcription by RNA polymerase II; cilium assembly; determination of left/right symmetry; digestive tract morphogenesis; fat cell differentiation; heart looping; intracellular protein localization; melanosome transport; pigment granule aggregation in cell center; non-motile cilium assembly
Cellular component: BBSome; centrosome; ciliary membrane; cytoplasm; axoneme; ciliary basal body; cytosol; membrane; neuron projection; centriolar satellite
Genetic constraint (gnomAD): Loss-of-function variants: 43 observed, 79.11 expected, observed/expected ratio (o/e) 0.54, 90% interval 0.43 to 0.7. The synonymous counts are far from expectation, so gnomAD's model fits this gene poorly and the ratio says little. Missense variants: 648 observed, 785.89 expected, observed/expected ratio (o/e) 0.82, 90% interval 0.77 to 0.88. Synonymous variants: 214 observed, 275.81 expected, observed/expected ratio (o/e) 0.78, 90% interval 0.69 to 0.87.
Gene-disease validity (ClinGen):
ClinGen rates the evidence that BBS7 causes each of these diseases.
BBS7-related ciliopathy (autosomal recessive): Definitive. Any ciliopathy caused by variants in the BBS7 gene.
Homologues: Orthologues: chimpanzee BBS7 (99% identical), macaque BBS7 (97% identical), dog BBS7 (95% identical), pig BBS7 (94% identical), rabbit BBS7 (93% identical), guinea pig BBS7 (92% identical), mouse Bbs7 (92% identical), rat Bbs7 (88% identical), tropical clawed frog bbs7 (83% identical), zebrafish bbs7 (76% identical), Caenorhabditis elegans osm-12 (34% identical).
Diseases named in the same sentence as BBS7 in open-access papers:
BBS7 is named in the same sentence as 22 diseases in open-access papers, as found by Europe PMC text mining. Sharing a sentence is not in itself a finding about the gene and the disease. The quoted sentences say what the papers report.
Bardet-Biedl syndrome (22 papers, 2008 to 2025). A ciliopathy with multisystem involvement. "According to literature data, the frequency of pathogenic variants in BBS7 is approximately 1.5%–3% of the patients with Bardet–Biedl syndrome." (PMID 39092430, 2024). "Results provided in this article show the significant role of pathogenic variants in the BBS7 gene for patients with Bardet–Biedl syndrome in the Russian population." (PMID 39092430, 2024). "The frequency of pathogenic variants in the BBS7 gene is about 1.5%–2% of patients with Bardet–Biedl syndrome, while in the cohort of Russian patients, the fraction is 24%." (PMID 39092430, 2024). "Previous work has shown that mutations in BBS-7, a conserved protein involved in trafficking of molecular cargos along the primary cilium of neurons, and linked to Bardet–Biedl syndrome, lead to increased neurosecretion from ADL." (PMID 35201977, 2022). "Patient 3 had Bardet–Biedl syndrome and carried a heterozygous mutation (c.389_390delAC; p.Asn130ThrfsTer4) in BBS7 and a homozygous mutation in BBS2 (c.209G>A; p.Ser70Asn)." (PMID 36672825, 2022). "Patient 2 had Bardet–Biedl syndrome with a homozygous frameshift mutation (c.389_390delAC; p.Asn130ThrfsTer4) in BBS7." (PMID 36672825, 2022). "Shaye and Greenwald showed that osm-12 (associated with osmotic stress response) is orthologous to BBS7 in man, which is associated to Bardet–Biedl syndrome." (PMID 24217915, 2014). "BBS-7 is one of a family of genes known to cause Bardet-Biedl Syndrome, a pleiotropic ciliopathy, in humans." (PMID 25486278, 2014). "The set of genes associated with Bardet-Biedl syndrome is represented in cluster A by the nodes BBS12, BBS10, and BBS7." (PMID 33805313, 2021). "The region on chromosome 8 that showed the highest contribution to the genetic variance of SFT harbours the BBS7 gene, which is involved in the occurrence of the Bardet-Biedl Syndrome (BBS)." (PMID 28831160, 2017). "We have identified the my13 lesion and found that it is a missense mutation in bbs-7, an ortholog of human BBS-7, a gene known to affect human cilia and to be involved in Bardet-Biedl syndrome." (PMID 25486278, 2014). "Although diabetes is one of the common features of Bardet-Biedl syndrome, the detailed relationship between BBS7 and diabetes remains unclear." (PMID 37051594, 2023). "Genetic defects in the Bbs7 gene contribute to Bardet–Biedl Syndrome in humans and mice." (PMID 36361806, 2022). "It has also been suggested that mutations in modifier genes are required for full penetrance of Bardet-Biedl Syndrome, making it possible that the observed bbs7 MO phenotypes may be specific to the genetic background in which they were observed." (PMID 24034702, 2013). "The BBS7 gene is a member of the Bardet-Biedl syndrome (BBS) family." (PMID 23241142, 2012). "Variant c.1967_1968delinsC in the BBS7 gene was described in a heterozygous state with another variant in one European patient with Bardet–Biedl syndrome (no data about ethnicity were contributed), but no information supporting the pathogenicity of this variant was provided." (PMID 39092430, 2024). "The higher frequency of this variant in the Russian population, as well as the lack of association of this pathogenic variant with Bardet–Biedl syndrome in other populations, suggests that the variant c.1967_1968delinsC in the BBS7 gene is major and has a founder effect in the Russian population." (PMID 39092430, 2024). "The higher frequency of this variant in the Russian population, as well as the lack of association of this pathogenic variant with Bardet–Biedl syndrome in other populations, suggests that variant c.1967_1968delinsC in the BBS7 gene is major and has a founder effect in the Russian population." (PMID 39092430, 2024).
Bardet-Biedl syndrome (continued). "Bardet–Biedl syndrome (BBS) was classified as a ciliopathy in 2003, and eight of the highly conserved BBS proteins (BBS1, BBS2, BBS4, BBS5, BBS7, BBS8, BBS9, and BBIP10) establish a stable protein complex called the BBSome that undergoes IFT." (PMID 37208194, 2023). "In Bardet–Biedl syndrome, TTC8, BBS9, WDPCP, and IFT27 were shared by the two pipelines, and BBS4, BBS7, BBS12, and IFT74 suffered significantly different selective pressures between TG and BG birds." (PMID 35456484, 2022). "Among these cases, 10 had Bardet-Biedl syndrome (BBS), comprising eight BBS2 patients and two BBS7 patients." (PMID 38671463, 2024).
Obesity (9 papers, 2007 to 2025). Accumulation of substantial excess body fat. "In contrast, reduced gene expression of Bbs7 in different tissues of BFMI mice in comparison to lean B6N control mice provided a hint on down-regulation as a potential mechanism causing obesity in BFMI mice." (PMID 36361806, 2022). "The Bbs7 gene was previously identified as the most likely causal gene for the obesity phenotype of the BFMI mouse." (PMID 34791189, 2022). "This marker was 604 kbp away from the Bbs7 gene that had been identified recently as causal gene for obesity in BFMI mice." (PMID 35729251, 2022). "The conducted genome-wide analyses of obesity-related traits in pigs revealed prominent genetic factors like MC4R and BBS7 with known contributions to monogenic and polygenic causes in the etiology of obesity." (PMID 28831160, 2017). "Beside obesity, molecular alterations of BBS7 are shown to be associated with secondary clinical features like developmental delay and hypertension." (PMID 28831160, 2017). "Other genes of interest that were more highly expressed after training included Haemoglobin subunit alpha and Bardet-Biedl syndrome 7 protein which affects early onset obesity causing hypertension and congenital heart disease." (PMID 29246115, 2017). "The deleted CTCF-element in intron 8 in BFMI, I8∆1, and I8∆2 may be responsible for reducing Bbs7 transcription levels, which might cause obesity by influencing fat deposition." (PMID 34910225, 2022). "In our BFMI mouse model, we could exclude the BBS7 protein variant as a causal factor for obesity, since this protein variant occurs in several mouse strains which are not obese (Ensembl release 102)." (PMID 36361806, 2022). "This indicates that in mice where the compensatory mechanism does not exist, the BFMI promoter variant could be causal for the down-regulation of Bbs7 and causing obesity." (PMID 36361806, 2022). "With regards to the significant associations between the BBS7 locus and fat thickness and leanness in pigs, this locus provides an interesting candidate not only for monogenic causes of obesity but also for its contribution to the polygenic implications on obesity rate." (PMID 28831160, 2017). "The small number of patients presenting with mutations in the BBS7 and BBS19 genes limits conclusions regarding their association with obesity." (PMID 40718228, 2025). "Obesity was most common in patients with BBS1 mutations, with 11 obese patients (78.6%) carrying BBS1 mutations, while patients with BBS7 and BBS19 mutations exhibited lower rates of obesity." (PMID 40718228, 2025). "In contrast, patients with mutations in the BBS7 and BBS19 genes had a significantly smaller proportion of obesity." (PMID 40718228, 2025). "Our results provide fundamental information on the transcriptional regulation of Bbs7 for future studies to fully unravel the molecular mechanism leading to obesity." (PMID 36361806, 2022). "Previous experiments on Bbs7 knockout mice showed obesity as one of the phenotypes observed in these mice." (PMID 34910225, 2022). "In this study, the targeted generation of the BFMI deletion in intron 8 of Bbs7 using CRISPR/Cas9 combined with complementation tests were used to identify the genetic effect of the deleted intron 8 region of Bbs7 on the development of obesity." (PMID 34910225, 2022). "Furthermore, complementation tests with different knockout mice in the target region revealed the Bardet Biedl syndrome 7 (Bbs7) gene as the most likely candidate for the juvenile obesity phenotype in BFMI mice." (PMID 34910225, 2022). "Therefore, we cannot exclude variants outside of the jObes1 locus that could affect or modulate the juvenile obesity phenotype in BFMI mice directly or in interaction with the deleted region in intron 8 of Bbs7." (PMID 34910225, 2022). "The significant point is that mice that do not develop obesity also do not show reduced Bbs7 expression." (PMID 36361806, 2022).
ciliopathy (7 papers, 2014 to 2025). A genetic disorder of the cellular cilia or the cilia anchoring structures, the basal bodies, or of ciliary function. "Other ciliopathy proteins including BBS1,2,4,6,7,8, NPHP5 and OFD1 also interact with proteasomal components, while loss of BBS4, BBS7 and OFD1 also resulted in a decrease of proteasomal activity." (PMID 29796181, 2018). "For ciliopathies involving Bbs7, compounds that enhance BBSome assembly could possibly prevent the protein mislocalization that drives photoreceptor death." (PMID 40558514, 2025). "Taken together, these results indicate that different ciliopathy-specific genes (BBS1, BBS7, BBS10 and TMEM216) modulate distinct aspects of apical–basal polarity of the RG scaffold and the integrity of the proliferative niche organization." (PMID 26206566, 2015). "Of the 30 ciliopathy genes tested, knockdown of four genes (BBS1, BBS7, BBS10 and TMEM216) resulted in disruption of the apical–basal polarity of RG cells." (PMID 26206566, 2015).
cone-rod dystrophy (2 papers, 2007 to 2022). Inherited retinal dystrophies that belong to the group of pigmentary retinopathies. "One example is a case of two brothers who have been diagnosed with BBS7, and both display a cone-rod dystrophy." (PMID 36125046, 2022).
retinal degeneration (2 papers, 2019 to 2025). Degeneration of the retina. "This dysfunction can exacerbate cellular stress and accelerate retinal degeneration, exposing a potential molecular mechanism underlying Bbs7-associated diseases." (PMID 40558514, 2025). "Disruption of Top2b activity could impair the expression of Bbs7, exacerbating protein mislocalization and catalyzing retinal degeneration." (PMID 40558514, 2025).
end-stage renal disease (1 paper, 2025). "In the present study, end-stage renal disease requiring dialysis was identified in one participant with BBS7-related BBS, one with BBS9-related BBS, and one with BBS1-related BBS." (PMID 40087798, 2025).
cancer (1 paper, 2025). A tumor composed of atypical neoplastic, often pleomorphic cells that invade other tissues. "These modules contained several cancer regulators such as Intraflagellar Transport (IFT) complex proteins (IFT74, IFT88), BBSome complex proteins (BBS2, BBS7, BBS9, BBS12), exocyst complex components (EXOC3, EXOC4, EXOC6B, EXOC7, and EXOC8), TTC8, TTC21B, EVC, and NEK1." (PMID 40700427, 2025).
Kidney disease (1 paper, 2025). "Kidney disease has been described as more prevalent in BBS2-, BBS7-, and BBS9-related BBS, as well as in BBS6-, BBS10-, and BBS12-related BBS." (PMID 40087798, 2025).
BBS7 also shares sentences with these, for which no sentence is quoted: Cognitive impairment (2 papers); congenital heart disease (1); developmental delay (1); diabetes (1); genetic disorder (1); Hearing impairment (1); Hypertension (1); Liver fibrosis (1); night blindness (1); Nystagmus (1); Photophobia (1); polydactyly (1); Retinal dystrophy (1); syndactyly (1).